SOX2 (SRY-box transcription factor 2)
Diseases named in the same sentence as SOX2 in open-access papers (continued):
Sharing a sentence is not in itself a finding about the gene and the disease.
cancer (continued). "Lin28 is the only RNA-binding protein among these genes and had also been reported to regulate SOX2 and Oct4 expression in cancer cells." (PMID 36428779, 2022). "Chromosome 3q25-26 is a frequently amplified locus in HNSCC that harbors multiple cancer-associated genes including WWTR1 (TAZ), PIK3CA, and SOX2." (PMID 35456049, 2022). "Among other functions, SOX2 promotes proliferation, survival, invasion, metastasis, cancer stemness, and drug resistance." (PMID 35886978, 2022). "Mounting evidence points to the role of SOX2 in enhancing drug resistance in several cancers, including glioblastoma, squamous cell carcinoma, gastric, breast, lung, and ovarian cancer." (PMID 35944584, 2022). "What is more, Forkhead box O-3a (Foxo3a)–SRY-related HMG-box-2 (Sox2) axis was first explored as the mechanism of ANGPTL1 regulated cancer migration, invasion, and stemness." (PMID 36156125, 2022). "One of the master modulators of pluripotency in cancer stem cells, SOX2 is located in an intronic region of SOX2OT long non-coding RNA." (PMID 36548179, 2022). "When we studied cancer stem cell markers Sox2 and Nanog, we observed that silencing of miR-124 upregulated both the stem cell markers significantly with a p-value of p<0.01." (PMID 36059695, 2022). "Briefly, we employed a SOX2-enhancer-GFP-reporter system to isolate cancer cells with high SOX2 transcriptional activity by FACS sorting." (PMID 36566021, 2022). "By analyzing the LUSC gene copy number profile, we identified SOX2 gene amplification in more than half of all patients with LUSC patients in The Cancer Genome Atlas (TCGA)." (PMID 36243874, 2022). "Decrease expression of FN1 and SOX2 indicating the inhibition of migration, invasion, and maintenance of cancer stem cell stemness." (PMID 36601474, 2022). "It demonstrated that Nanog and Sox2 are the key transcription factors who regulate the gene expressions during the process of enrichment of cancer stem cells." (PMID 36402751, 2022). "ALDH1, OCT4, SOX2 and Nanog are all markers of the stemness state of cancer stem cells and are important in maintaining the nature and drug resistance of cancer stem cells." (PMID 35242031, 2022). "In this study, we confirm that cancer cell stemness is required for the maintenance of an OPN-induced myCAF phenotype.Methods: MDA-MB-231 or HepG2 cells and Sox2 knockout variants were co-cultured with human mesenchymal stem cells (MSC)." (PMID 36284815, 2022). "SOX2-high cancer cells showed CSCs features, such as greater mammosphere forming ability, validating that this sub-population was enriched in CSCs." (PMID 36566021, 2022). "SOX2 is involved in the maintenance of an undifferentiated cellular phenotype and often leads to increased chemotherapy resistance in cancer." (PMID 35740372, 2022). "NF-κB has been suggested to regulate CD44, SOX2, OCT4, and OILG2 expression in association with cancer cell invasiveness or stemness in different cancer models." (PMID 35906203, 2022). "The transcription factor sex determining region Y-box2 (SOX2) was a regulator of cancer stem cell stemness and tumorigenicity, which helps cancer cells evade immune surveillance and resist apoptosis." (PMID 36119495, 2022). "Thymoquinone also altered the expression of the target gene of the NF-κB pathway, such as Sox2 and Nanog, involved in proliferation and survival of cancer cells and cancer stem cells." (PMID 36354700, 2022). "The combined drug treatment led to reduced mRNA expression of OCT-4, SOX-2 and Nanog in the cancer stem cells tested, suggesting the reduced stemness of the cells." (PMID 35677165, 2022). "Consistently with previous studies, our results indicate that SALL4 in concert with other stemness markers like OCT4, NANOG, and SOX2 can drive reprogramming of cancer cells toward a CSC-like phenotype mediated by the TWIST1 expression." (PMID 36474162, 2022).
cancer (continued). "The genetic regulators that are involved in pluripotency also become upregulated (such as sox2, oct4, c-myc), finally contributing to the development of cancer stem cells." (PMID 35538578, 2022). "Increased self-renewal of cancer cells is caused by commonly found copy number amplifications of the transcription factors (TFs) TP63 and SOX2, which promote survival and inhibit squamous differentiation." (PMID 35159370, 2022). "Surprisingly, it is clarified that mTOR upregulation and reduced upstream AMP-activated protein kinase levels are indispensable to converting cancer cells to cancer stem-like cells mediated by Sox-2 overexpression in reprogrammed breast cancer cell lines." (PMID 36064437, 2022). "Meanwhile, the score of SOX2, known as a key driver in cancer stemness, was increased in patients with recurrence compared with controls without recurrence." (PMID 35954313, 2022). "Our results showed that SJZ treatment inhibited the spheroid and colony-forming capacities of SGC7901 cells, accompanied by downregulation of cancer stem cell markers such as SOX2, NANOG, and CD44." (PMID 35873650, 2022). "EMT reversal was established through increased E-cadherin and reduced N-cadherin while inhibition of cancer stem cell phenotype was evident through reduced Sox2 and Nanog." (PMID 36059695, 2022). "Lastly, circ_001680 has been found to promote several cancer stem cell characteristics, such as sphere formation ability, elevated expression of stem cell characteristic markers (SOX2, CD44, and CD133), and irinotecan resistance." (PMID 36429127, 2022). "Reducing the expression levels of SOX2 can be therapeutically beneficial for decreasing chemoresistance by decreasing the population of cancer stem cells." (PMID 36551731, 2022). "Higher resistance to cancer treatment has been linked to the presence of key regulators of strain self-renewal, including octamer-binding transcription factor 4 (OCT4), sex-determining region Y-box 2 (SOX2), and the Nanog homeobox (NANOG)." (PMID 36439901, 2022). "It suggested that transcription factors such as Sox2 and Nanog play roles in different phases of cancer stem cell enrichment." (PMID 36402751, 2022). "Although no universally accurate markers for GBM stem cells exist, among the most frequently used markers for detection of GBM cancer stem-like cells, are SOX2 and Nestin." (PMID 36038950, 2022). "Positive correlations between the expression levels of NINJ1 and SOX2 were observed in these cancers." (PMID 35395804, 2022). "MYC is a gene frequently involved in cancer, and it is one of the four genes (in addition to Oct4, Sox2, and Klf4) that can reprogram fibroblasts to become pluripotent stem cells." (PMID 34991589, 2022). "Using chromatin immunoprecipitation sequencing (ChIP-seq), we showed that SES- and SOX2-bound genomic sites in cancer cells are similar to the endogenous SOX2 footprint in human neural precursors (NPCs) and, to a lesser extent, in embryonic stem cells (ESCs)." (PMID 35921410, 2022). "The dysregulated expression of SOX2 results in tumorigenesis and therapy resistance in various cancer types." (PMID 36243874, 2022). "Several studies have suggested that the PI3K/AKT pathway cooperatively interacts with SOX2 in cancer." (PMID 36118530, 2022). "On the contrary, interactions of EphB1 and ligand ephrinB2 in trans promoted the stemness of cancer cells through upregulating Sox2 during the shift from cellular dormancy to reactivation." (PMID 36402751, 2022). "Together, these findings indicate that SOX2 elevation downregulates the expression of MYC target genes in two diverse human cancer types." (PMID 35454854, 2022). "Its role in both cancer and developmental systems has been widely studied and it has been shown to form a complex with SOX2." (PMID 36413568, 2022). "Another study revealed a significant correlation of TAM counts with the expression of cancer stem cell markers SOX2 and ALDH1." (PMID 36143308, 2022).
cancer (continued). "SOX2 antagonizes Hippo signaling to maintain cancer cell stemness, while YAP can regulate SOX2 to facilitate self-renewal and vascular mimicry of “stem-like” cancer cells." (PMID 35737114, 2022). "Mounting evidence suggests that SOX2 inhibits apoptosis and subsequently drives chemoresistance in various types of human cancers." (PMID 35309116, 2022). "UBCH10, a cancer-related E2 ubiquitin-conjugating enzyme, is highly expressed in human lung SCCs and upregulates the expression of Twist1, c-Myc, and Sox2." (PMID 36270982, 2022). "Herein, we describe a new model system to isolate stem-like cancer cells, based on the functional transcriptional activity of SOX2." (PMID 36566021, 2022). "ALDH1, OCT4, SOX2 and Nanog are all stemness markers of cancer stem cells and have important roles in maintaining the nature of cancer stem cells and drug resistance." (PMID 35242031, 2022). "Previous studies had shown that cancer stem cells maintain their stem cell-like biological characteristics through a high expression of specific stemness markers (such as SOX2, CD44, CD133, and MYC)." (PMID 35859724, 2022). "Dinaciclib suppressed SOX2 mRNA expression in these cancer cells and the number of sphere-forming cells from the HCT116, SW480, and H460 lines." (PMID 35190631, 2022). "We demonstrated that HRASV12-induced cyclin-dependent kinase 1 (CDK1) activity and subsequent enhancement of protein O-GlcNAcylation were required for SOX2 induction and CSC generation in these fibroblasts and cancer cell lines containing RAS mutations." (PMID 35190631, 2022). "Emerging data have revealed that SOX2 is involved in many molecular events and has a key role in cancer." (PMID 35059870, 2022). "Resveratrol also suppressed Sox2 expression and activated Akt and STAT3 that are induced by cancer-associated fibroblasts." (PMID 35566016, 2022). "In recent years, the aberrant expression of sex-determining region Y (SRY)-box 2 (Sox2) has been detected in a wide diversity of cancers." (PMID 35565425, 2022). "In bladder cancer, the over-expression of METTL3 increases m6A methylation status, regulates the expression of AFF4, promotes its transcription by combining with the promoter region of Sox2, and promotes the self-renewal of cancer stem cells." (PMID 35022030, 2022). "In cervical cancers, the elevated levels of UCA1 sequester miR-122-5p to upregulate Sox-2 expression, thereby facilitating cancer stemness." (PMID 36010595, 2022). "Recently studies reported that SOX2 controls a network of coding and non-coding RNAs in cancers and identified a set of miRNAs as critical down-stream mediators of SOX2 function." (PMID 35236826, 2022). "Sex determining region Y-box 2 (SOX2) promotes cancer cell proliferation and tumorigenesis and reduces apoptosis." (PMID 36247876, 2022). "Sequestration of miR-145-5p by lncRNA-MACC1-AS1 induces the expression of stemness markers CD133, OCT4, and SOX2, and increases both oxaliplatin resistance and tumorigenic capacity of cancer cells." (PMID 35954194, 2022). "In cancer cells, the capacity for migration, proliferation, clonogenicity and stemness increases, with a clear change in the expression of Nanog, Oct4 and SOX2 transcription factors." (PMID 36232741, 2022). "Oct-4, Nanog, and Sox-2 were studied in surrogate GBM cells to delineate probable mechanistic effects in cancer stem cells." (PMID 35804970, 2022). "SOX2 was reported to promote the degradation of STING protein in an autophagy‐dependent manner in cancer cells." (PMID 35415876, 2022). "Based on the expression of Sox2 in KC tumors and the noteworthy contributions to the biology of these cancers, characterizing corollaries between Sox2 and clinical parameters is warranted." (PMID 35892887, 2022).
cancer (continued). "Previous studies have elucidated that SOX2 plays vital roles in cancer cells proliferation, migration, and invasion." (PMID 35236826, 2022). "Sox-2 promotes chemoresistance, maintains cancer stem cell properties, and induces epithelial-mesenchymal transition." (PMID 36601474, 2022). "Together, these results demonstrate that SOX2 elevation decreases protein translation across multiple human cancer types." (PMID 35454854, 2022). "Data from the TCGA Pan-Cancer Atlas Studies were used for survival analysis, and higher SOX2 expression correlated with much shorter disease-free survival and overall survival." (PMID 35382656, 2022). "SOX2 expression also has been correlated with clinical parameters, such as staging, relapse, therapy resistance, and prognosis of patients in various cancers." (PMID 35055392, 2022). "Previous work from our laboratory has demonstrated that elevating SOX2 from a doxycycline (Dox)-inducible promoter inhibits the proliferation of multiple human cancer types." (PMID 35454854, 2022). "Recently, aberrant expression of SOX2 has been demonstrated in various types of cancers, including NSCLC." (PMID 35059870, 2022). "The stem cell transcription factor SOX2 plays diverse and critical roles during mammalian development and cancer." (PMID 35454854, 2022). "On the whole, it was found that aberrant expression of miR-22 is relevant to cancer stem cell transcription factors (SOX2 and OCT4) in CRC cells." (PMID 36061355, 2022). "On the contrary, in the state of MET, in which cell-cell adhesion was recovered, interactions of EphB1 and ligand EphrinB2 in trans promoted the stemness of cancer cells through upregulating Nanog and Sox2." (PMID 36402751, 2022). "Oct4, Nanog, and Sox2 are highly expressed in CSCs in different cancers and recognized as the most important transcriptional factors to regulate stem cell pluripotency, renewal, and maintenance." (PMID 35912174, 2022). "Further, our immunoblotting and immunoflurescence data showed that CSC specific transcription factors, Sox-2, Oct 3/4 and Nanog were enhanced in cancer cells upon treatment with IL-6." (PMID 35300689, 2022). "WT mouse CRIPSCs also had higher expression of the genes related to stem cells (Psca, Atg9b, Sox2, Sox9), cell cycle (Cdk6), mammary luminal progenitor cells (Notch3 and Notch1), and cancers." (PMID 35841025, 2022). "Enhanced expressions for cancer stem cell markers Sox2, POU5F1(Oct4), Nanog, ALDHA1 and CD133 were observed in dormant and reactivated cancer cells after treatment of cisplatin." (PMID 36402751, 2022). "The findings presented in this study provide novel insights into the molecular mechanisms through which elevated SOX2 restricts the proliferation of multiple human cancer types." (PMID 35454854, 2022). "SOX2 regulates its target genes to promote cancer cell growth, invasion, migration, metastasis, and chemoresistance." (PMID 36118530, 2022). "Sox2 is a transcription factor essential for self‐renewal of neural and the cancer stem cell population reported to drive relapse in Shh MB." (PMID 34482626, 2022). "Gene expression profiling suggested a dynamic regulatory mechanism during the process of enrichment of cancer stem cells, where Nanog showed upregulation in the dormant state and SOX2 showed upregulation in the reactivated state." (PMID 36402751, 2022). "We also checked the cancer stem cell markers, Sox2 and Nanog in both of these CTCL cells and observed that both the markers, that we evaluated, were significantly reduced upon silencing of MALAT1 in HH as well as in H9 cells." (PMID 36059695, 2022). "Numerous studies have shown that the key regulators in maintaining the stemness of embryonic stem cells, including Oct4, Sox2, and Nanog, along with their activation targets, are commonly overexpressed in cancer stem cells in several malignancies." (PMID 35965510, 2022).
cancer (continued). "SOX2, a member of the SRY-related HMG-box (SOX) family, is abnormally expressed in many tumors and associated with cancer stem cell-like properties." (PMID 36293387, 2022). "Numerous studies have reported aberrant expression of SOX2 in cancer (see review), and SOX2 is recognized as a powerful oncogene, where it regulates cancer stem cells." (PMID 36012592, 2022). "Cell cycle arrest and chemotherapy resistance are other features of cancer stem cells, and we detected changes in the cell cycle after knocking out Sox2 or Klf4 under hypoxia." (PMID 33762574, 2021). "STAT3 signaling was found to be an important pathway involved in the transcriptional regulation of Sox2 to promote the stemness of cancer cells." (PMID 33456560, 2021). "Mechanistically, high levels of BCAT1 depleted α-ketoglutarate (α-KG) and promoted expression of SOX2, a transcription factor regulating cancer cell stemness and metastasis." (PMID 34646394, 2021). "Inhibition of HDAC11 not only significantly reduces self-renewal capacity of cancer stem cells from NSCLC but also decreases SOX2 expression that is essential for their maintenance." (PMID 34487971, 2021). "SOX2 overexpression in cancer cells has been largely attributed to copy number amplifications of the SOX2 gene itself." (PMID 34880227, 2021). "Western blot analysis showed that the expression of cancer stem cell related genes, such as SOX2, OCT4 and CD133, was reduced following SETD1A knockdown." (PMID 34645486, 2021). "This mutation also induced an increase in the cancer stem cell pool and the expression of NANOG, OCT4, and SOX2." (PMID 34066428, 2021). "In this study, SOX2 protein levels appeared to correlate with SOX2 amplification, supporting the notion that it plays a role in cancer development and that overexpression of SOX2 to some extent is dependent on amplification." (PMID 34069138, 2021). "SOX2 is expressed in cancer cells and regulates their proliferation, migration, invasion, and metastasis." (PMID 33795719, 2021). "qRT‐PCR showed that circFAT1 KD significantly inhibited the expression of the cancer stemness‐related genes, including SOX2, KLF4, MET, BMI1, CD24, OCT4, and ALDH1, in ALDHhigh SCC23 cells." (PMID 34258151, 2021). "For example, dysregulation of cell-fate-specifying transcription factors, such as Sox2 and Nkx2.1, can contribute to lineage plasticity and stemness in cancer cells." (PMID 34618689, 2021). "In conclusion, our data reveal that SRR2 deletion halts malignant activity of SOX2 and confirms that the SRR2 enhancer regulates SOX2 expression in cancer." (PMID 33805518, 2021). "Further, treatment with EC359 reduced the spheroid formation of EC cancer stem cells and reduced the levels of cancer stem cell markers SOX2, OCT4, NANOG, and Axin2." (PMID 34400617, 2021). "The increased expression of self-renewal regulatory factors important in cell pluripotent state such as OCT4, NANOG and SOX2 was detected in various types of cancers." (PMID 33471801, 2021). "This was accompanied by inhibition of EMT and downregulation of EMT-modulating factor Notch1, β-catenin activity and the cancer stem cell marker Sox2." (PMID 34485294, 2021). "In tongue squamous cell carcinoma, Sox2 overexpression was associated with EMT progression, suggesting its involvement in regulation of cancer cell motility." (PMID 34195082, 2021). "Constitutive expression of SOX2 in HNSCC cells was shown to generate a cancer stem cell-like phenotype." (PMID 33671869, 2021). "Another well-known transcriptional factor is Sex-determining region Y-box 2 (SOX2), which is an essential in the self-renewal and pluripotency of embryonic stem cells, affecting in cell survival and progression of cancers." (PMID 34731191, 2021). "SOX2-expressing cancer cells, such as those in skin and bladder carcinomas, express high levels of CSC markers, depending on tissue origin, and reveal enhanced tumorigenicity." (PMID 33445526, 2021).